RNU7-134P (RNA, U7 small nuclear 134 pseudogene)
Gene: Small nuclear RNA gene on chromosome 17 (57,685,529 to 57,685,592, reverse strand). Ensembl gene ENSG00000238447.
Homologues: Orthologues: macaque U7 (88% identical). Paralogues in human: RNU7-9P (80% identical), RNU7-34P (78% identical), RNU7-65P (78% identical), RNU7-79P (78% identical), RNU7-27P (77% identical), RNU7-60P (77% identical), RNU7-62P (77% identical), RNU7-70P (77% identical), RNU7-80P (77% identical), RNU7-84P (77% identical), U7 (77% identical), RNU7-1 (75% identical), and 141 more.